INS (insulin)
Diseases named in the same sentence as INS in open-access papers (continued):
Sharing a sentence is not in itself a finding about the gene and the disease.
Hyperglycemia (continued). "Diabetes mellitus is a disorder characterised by modifications in glucose homeostasis and ineffective secretion or action of insulin and, if not managed appropriately, leads to the development of hyperglycaemia." (PMID 29181404, 2017). "During the non-systematic transition of care, the hyperglycemia was not communicated or noted, which led to a delay in the administration of insulin therapy and increased ED length of stay." (PMID 28435497, 2017). "Metabolic tests composed of IPGTT, ITT, GSIS, and HOMA-IR in our research indicated that stressed mice got insulin-resistant phenotypes, but were not obvious in hyperglycemia." (PMID 29084550, 2017). "This severe hyperglycaemia was not due to exhaustion of the insulin content of the pellets, because streptozotocin-treated non-pregnant females did not develop hyperglycaemia after insulin pellet implantation during a similar period of time." (PMID 28341857, 2017). "Early administration of amino acids is expected to prevent hyperglycemia and nonoliguric hyperkalemia by stimulating insulin secretion and inhibiting cellular catabolism." (PMID 29104345, 2017). "The control of hyperglycaemia with insulin administration was not enough for preventing the progression of renal fibrosis." (PMID 29196746, 2017). "Earlier studies suggested that non-diabetic patients with sustained hyperglycemia benefit greatly from tight glycemic control (target level of 80–110 mg/dL) by using insulin therapy, which can reduce mortality significantly among medical and surgical patients." (PMID 28107491, 2017). "Second, hepatocyte MPC disruption consistently decreases HFD-induced hyperglycemia without apparent changes in peripheral insulin sensitivity." (PMID 29107293, 2017). "The NIRTURE trial of early insulin treatment was the first large trial (N = 389) that used CGM without real-time display to detect hyperglycaemia in very low birthweight babies." (PMID 29051825, 2017). "Due to its breadth of usability, insulin remains the main agent for controlling hyperglycemia for in-hospital patients, and can be used regardless of comorbidities or altered clinical states such as impaired renal function and decompensated cardiac failure." (PMID 28265893, 2017). "So it was indicated that current clinical evidence mainly supported that garlic supplement would further enhance the therapeutic effect of other hyperglycemia drugs and insulin, but was not completely the significant effect of garlic alone." (PMID 29056888, 2017). "The path coefficient for BMI → insulin was significantly greater in MetS than in non-MetS groups (0.510 vs 0.190, p < 0.001), and greater in hyperglycemia than in normoglycemia groups (0.503 vs 0.285, p = 0.026)." (PMID 28230104, 2017). "Hyperinsulinemia rather than hyperglycemia can accelerate the progression of HCC via insulin signaling." (PMID 28903776, 2017). "Type 1 diabetes is caused by an autoimmune reaction towards β-cells, resulting in a lack of insulin secretion, leading to hyperglycemia." (PMID 28025655, 2017). "Individuals who reported not using insulin at registration experienced the biggest reduction in days with hyperglycemia by 25.2%, but also experienced an overall increase in hypoglycemic events of 6.7% starting in month 6 of the program (bottom)." (PMID 28698167, 2017). "Together, our data suggest intermittent hypoxia produces hyperglycemia independent of changes in insulin resistance, at least initially." (PMID 28087818, 2017). "The kidney PGC-1α levels did not change in the short-period group, whereas in the long-period group, the reduced PGC-1α expression levels observed after 24 weeks of hyperglycemia were not normalized by the combined insulin/metformin treatment." (PMID 28079150, 2017). "Without the liver sensing insulin, there is decreased hepatic glucose uptake from the portal vein after a meal, and pronounced post-prandial hyperglycemia." (PMID 29127952, 2017).
Hyperglycemia (continued). "For hyperglycemia resulting from intra-articular steroid injection, as with multiple daily steroid doses, oral agents are unlikely to control the hyperglycemia, and a subcutaneous insulin regime is preferred." (PMID 28265893, 2017). "Despite similar food intake male ERV1tg mice gained significantly less weight, did not develop fasting hyperglycemia and had normal insulin sensitivity after 5 months of HFD feeding compared to WT mice." (PMID 28993702, 2017). "There were no statistical differences in 30-day mortality and hyperglycaemia requiring insulin treatment in the propensity score analysis between the no-corticosteroid and low-dose corticosteroid groups." (PMID 29284447, 2017). "In healthy young men, exercise-induced glycogen depletion combined with dietary carbohydrate restriction promotes insulin sensitivity, but no studies have tested this effect in subjects with hyperglycemia." (PMID 29387730, 2017). "Exercise in our patient modestly improved glycemic control, due to its beneficial effects on insulin sensitivity and hyperglycemia, however this was not enough." (PMID 29127952, 2017). "The aim of this study was to investigate the effects of Cyclocarya paliurus extract (CPE) on insulin signaling and its capacity to correct hyperglycemia in the absence of insulin." (PMID 28859155, 2017). "Although intraportal transplantation of ICCs did not reverse hyperglycemia in any of the six recipients, insulin synthesis and secretion were partially restored." (PMID 28566744, 2017). "Nevertheless, the hyperglycemia frequency perception was worse in the insulin-treated LADA patients, although glycemic control was not different between the groups." (PMID 29062603, 2017). "Despite the relatively increased frequency of hyperglycemia, our protocol does not lead to clinically relevant hypoglycemia and provides a safe model of calculating insulin doses for CSII in children." (PMID 28484424, 2017). "MIN6 cells strongly expressed both ORAIP and insulin in granule-like morphology under high concentration (25.0 mM) of glucose, strongly suggesting that the pancreatic β-cells secrete ORAIP as well as insulin in response to hyperglycemia." (PMID 29057797, 2017). "MK-2305-mediated changes in glucose were coupled with increases in plasma insulin during hyperglycemia and glucose challenges but not during fasting, when glucose was normalized." (PMID 28542610, 2017). "Despite these findings, there remains a lack of evidence guiding the management of hyperglycemia in the pediatric TBI population which is reflected in a marked disparity in insulin regimens and glucose targets worldwide." (PMID 28993802, 2017). "In mice, QRFP26 attenuated glucose-induced hyperglycemia, increased insulin sensitivity and plasma insulin concentrations but did not alter basal glycemia, suggesting antihyperglycemic action." (PMID 28729853, 2017). "This may depend on the improved glucose-insulin homeostasis and lower levels of GIP, because GIP together with hyperinsulinemia and hyperglycemia is strongly involved in lipid regulation in humans." (PMID 27664051, 2016). "In our induction strategy, about 15% of differentiated hMSCs express insulin in vitro, which will not be enough to correct hyperglycemia of the transplanted mice when using 106~107 differentiated cells/mouse in vivo." (PMID 26756576, 2016). "DPP-4 inhibitors also prevent the degradation of insulin secretagogues such as glucagon-like peptide-1 (GLP-1), thereby ameliorating hyperglycaemia without causing hypoglycaemia." (PMID 26767505, 2016). "We have previously shown that DeMeth insulin cfDNA levels are increased during the natural progression of T1D in the NOD mouse and are reduced following the development of hyperglycemia, demonstrating the utility of DeMeth insulin DNA as a biomarker of insulin-expressing β-cell death in prediabetes." (PMID 27111653, 2016).
Hyperglycemia (continued). "A limitation of the present study is the HFD model itself, which does not allow separating the effects of hyperglycaemia per se, insulin resistance, excess body weight and ageing on the skeletal response." (PMID 27759061, 2016). "When hyperinsulinemia can no longer compensate for IR and insulin secretion begins to decline, the disruption of these variables results in hyperglycemia and a diagnosis of DM." (PMID 27471550, 2016). "Predominantly, rapid-acting insulin was used to manage hyperglycemia in patients without pretransplant DM." (PMID 28031946, 2016). "The high insulin content in the pancreases of adult Aldh1b1tm1lacZ null mice at week 8 partially compensated for functional defects and delayed the onset of hyperglycaemia, which became evident from week 12 and worsened progressively with age." (PMID 26518685, 2016). "A desirable profile of insulin in rodents includes reduction of hyperglycemia without large fluctuations or hypoglycemic episodes to mimic the desired profile of insulin in T1DM patients." (PMID 27253523, 2016). "We observed an age‐associated increase in fasting insulin levels in males, as well as fasting hyperglycemia in Old male mice, but no change in fasting glucose or insulin levels with age in females." (PMID 26695882, 2016). "Interestingly, the mRNA levels of FoxO1 target genes in skeletal muscle were strongly upregulated, reflecting insulin signaling insufficiency, after DT and STZ+S961, the two conditions that led to hyperglycemia." (PMID 27092792, 2016). "The induced increase in insulin synthesis could compensate for the damage triggered by STZ and prevent the initial development of hyperglycemia." (PMID 27790217, 2016). "SIK2 functions as a negative modulator of the insulin-dependent survival pathway and contributes to hyperglycemia-induced cell death of Muller glia." (PMID 27504893, 2016). "Taken together, these results suggest that ALA combined with ferrous ion is effective in reducing hyperglycemia of T2DM without affecting plasma insulin levels." (PMID 27239432, 2016). "The effects of hyperglycemia on the epidermis were examined in streptozotocin-induced diabetic mice with/without insulin therapy." (PMID 27846299, 2016). "Hearts from obese and insulin-resistant rodent models (ob/ob and db/db mice) exhibit higher rates of fatty acid (FA) oxidation and MVO2, but lower rates of glucose oxidation and cardiac efficiency, which precede the development of hyperglycemia." (PMID 27148064, 2016). "Embryonic hyperglycemia, therefore, most likely exerts its teratogenic effects in the absence of insulin, that is, directly on sensitive cells via glucose transporters or as osmolyte." (PMID 27433804, 2016). "In addition, even in our patients with premorbid insulin-dependent diabetes, the majority of which also required insulin in ICU, early ketosis resolved despite sustained hyperglycemia." (PMID 27633987, 2016). "Adiponectin was also reported to be inversely correlated with body fat percentage in adults and to mediate insulin-sensitizing effect to ameliorate hyperglycemia and hyperinsulinemia without inducing weight gain or even inducing weight loss." (PMID 27123038, 2016). "However, because the insulin concentration of the culture medium was constant in our in vitro studies of islets and INS-1 cells, the changes we observed must be a function of hyperglycaemia." (PMID 27882918, 2016). "In conclusion, our current findings provide strong evidence that procyanidin cinnamtannin A2 (PA4-2) prevent hyperglycemia and ameliorate glucose tolerance through promoting GLUT4 translocation and enhancing glucose uptake by incretin hormone GLP-1 driven activation of insulin signaling pathway." (PMID 27598258, 2016). "Short acting rapid insulin before meals remains the insulin of choice for those without fasting hyperglycaemia." (PMID 27872738, 2016).
Hyperglycemia (continued). "Each patient received multiple daily insulin injection therapy or continuous subcutaneous insulin infusion therapy, and glycemic control without hypoglycemia and hyperglycemia, pre- and post-combat sports, was expected to be very difficult." (PMID 29910276, 2016). "Yet, despite the use of insulin therapy in clinical T1DM, it is often the case that chronic, moderate hyperglycemia is maintained as a result of difficulties in regulating [BG] in response to dynamic influences on glycemic control, such as food intake and exercise." (PMID 26885531, 2016). "The pancreatic islets were smaller in size and disordered and the insulin secretion was affected in F1 offspring of mothers with GDM, indicating that intrauterine hyperglycemia may lead to abnormal structure of fetal islets." (PMID 26881249, 2016). "According to 13 articles, insulin was the treatment of choice if diet alone was not sufficient to control hyperglycemia." (PMID 27803934, 2016). "In the beginning, hormone effects do not alter the target tissues for insulin action but as the disease progresses there is an increase in insulin concentrations and postprandial hyperglycemia occurs." (PMID 27376154, 2016). "Taken together with our findings, these results suggest that the β-cell enlargement and attendant insulin secreting capacity earlier in pregnancy is not related, and certainly not reactive, to control of hyperglycemia." (PMID 27559358, 2016). "Diabetes mellitus refers to a heterogeneous group of metabolic diseases characterized mainly by hyperglycemia resulting from a lack of secretion and/or action of insulin." (PMID 26841874, 2016). "Intravenous (IV) insulin therapy with or without adjunctive subcutaneous insulin therapy is the mainstay of managing hyperglycemia in perioperative period." (PMID 25874191, 2015). "In the process of T2D, hyperglycemia and hyperlipidemia could activation JNK phosphorylation to augment Forkhead box protein O1 (FOXO1), which is a transcription factor to regulate insulin synthesis in β-cells." (PMID 26147439, 2015). "Since miR-15b and miR-16 target many genes, including downstream molecules of insulin signaling, it is probable that signaling pathways, other than insulin signaling, are activated to maintain normal cell signaling in transfected REC in response to hyperglycemia." (PMID 25888955, 2015). "Before discharge the patients with hyperglycemia are stabilized and usually do not require insulin therapy." (PMID 25874191, 2015). "Glucose infusion rate (GIR) and GIR normalized to body weight necessary to maintain hyperglycemia were not significantly different between treatments (p > 0.25), consistent with similar acute effects of the treatments on insulin sensitivity." (PMID 25811109, 2015). "Although it has a number of direct detrimental effects on the ischemic myocardium, hyperglycemia is also representative of an acute metabolic stress characterised by high adrenergic-mediated levels of free fatty acids (FFA), insulin resistance and impaired glucose utilization." (PMID 26253538, 2015). "Our results remained essentially unchanged at high glucose concentration (16.7 mM) indicating that simvastatin’s effect on insulin secretion is not substantially affected by the presence of hyperglycemia." (PMID 26561346, 2015). "B6-ob/ob mice lacking leptin on the C57BL/6 background become obese and insulin resistant but do not develop hyperglycemia because of massive beta-cell proliferation and high serum insulin levels." (PMID 26348837, 2015). "Should hyperglycaemia remain an issue at near-maximum dose, initiation of insulin should be contemplated rather than the addition of an alternative oral hypoglycaemic agent as these act too slowly to be beneficial in this circumstance." (PMID 26550039, 2015).
Hyperglycemia (continued). "This relative hyperglycemia at night in rats without pineal gland is not due to a reduced insulin secretion to meal cues because in hamsters exposed to long photoperiod, mean insulin levels were not significantly affected by pinealectomy." (PMID 26074760, 2015). "In the pediatric patients, the hyperglycemia is insulin reversible, insulin is absent from circulation following an ASNase therapeutic regimen that includes steroid hormones similar to prednisolone, and it is likely that central control over insulin synthesis or release may be deficient." (PMID 26178806, 2015). "Physiologic replacement of insulin can be mediated by a long-acting basal insulin dose (regardless of alimentation status), short or rapid acting insulin dose following meals, and rapid acting supplemental insulin to combat hyperglycemia if needed." (PMID 26078998, 2015). "We found that TRB3-short hairpin RNA (shRNA) lentiviral infection reduced TRB3 expression but did not change hyperglycaemia and plasma level of insulin or IGF-1." (PMID 26268733, 2015). "The insulin-producing pancreatic islet beta cells were destroyed and elevated blood glucose levels were detected within 2 weeks after 5-day consecutive low-dose (50 mg/kg) STZ injection and remained hyperglycemia until sacrifice." (PMID 26337468, 2015). "When SIRT1 or the deacetylase inactive version of SIRT1 (H363Y) were over expressed in muscle, there was no alteration of the insulin resistance that occurs with 5h of hyperglycaemia." (PMID 25798922, 2015). "While hyperglycemia in patients with T2DM may be initially managed with oral antidiabetes medications alone, added insulin therapy often becomes necessary with longer duration of disease." (PMID 26060825, 2015). "Moreover, their preclinical study shows that continuous systemic leptin administration ameliorates hyperglycemia and that it can reduce dosage of insulin for anti-diabetic treatment, suggesting that leptin may be applicable in the clinical setting as an adjuvant to insulin therapy." (PMID 25870537, 2015). "DM is characterized by marked high levels of blood glucose and occurs in two forms: type 1 DM (T1DM), which results from insulin deficiency, and type 2 DM (T2DM) which starts with overproduction of insulin due to insulin resistance and over time results like T1DM in extreme hyperglycemia." (PMID 26617484, 2015). "She stayed for 3 months without insulin but later presented with hyperglycemia and pre-mixed insulin was reintroduced at 4 IU per day." (PMID 26966489, 2015). "The effects of simvastatin treatment on insulin secretion were not affected by the presence of hyperglycemia." (PMID 26561346, 2015). "Type II diabetes (T2D) is non-insulin-dependent diabetes and it is mainly characterized by insulin resistance with subsequently relative lack of insulin and hyperglycemia, for which beta cells in contrast can still produce and secrete insulin." (PMID 25898945, 2015). "In GK rat skeletal muscle exposed to hyperglycemia in vivo, increased phosphorylation of PKCα, PKCδ and PKCζ indicated defective insulin signalling, and this was not corrected by acute normalization of glycemia." (PMID 26398746, 2015). "Twice-daily administration of [L28K]esculentin-2CHa for 28 days did not affect body weight and food intake but reduced hyperglycaemia and elevated plasma insulin concentrations in the non-fasting state." (PMID 26512980, 2015). "The relation between hyperglycemia and abnormal SNS is further supported by the observation that reducing blood glucose with insulin can attenuate cardiac autonomic neuropathy in type-1 DM patients as well as reduce NE and restore cardiac NET expression in STZ rats." (PMID 25996498, 2015). "Although reprogrammed hepatocytes or ductal cells in the liver were able to secrete insulin and ameliorate hyperglycemia, full conversion into bona-fide (mature) β cells was not achieved." (PMID 26690959, 2015).